TAS2R9 (taste 2 receptor member 9)
Description:
Gustducin-coupled receptor implicated in the perception of bitter compounds in the oral cavity and the gastrointestinal tract. Signals through PLCB2 and the calcium-regulated cation channel TRPM5 (By similarity).
Synonyms: T2R9; TRB6
Tractability: Antibody: its Gene Ontology location is reachable by antibodies, with high confidence; UniProt predicts a signal peptide or a membrane-spanning region. PROTAC: a small molecule that binds it is known.
Target class: Membrane receptor; Taste receptor (taste family GPCR); Taste family G protein-coupled receptor
Gene: Protein-coding gene on chromosome 12 (10,809,094 to 10,810,168, reverse strand). Ensembl gene ENSG00000121381.
Subcellular location: Membrane
Pathways (Reactome):
Signal Transduction: Class C/3 (Metabotropic glutamate/pheromone receptors); G alpha (i) signalling events
Gene Ontology:
Molecular function: bitter taste receptor activity; taste receptor activity; G protein-coupled receptor activity
Biological process: detection of chemical stimulus involved in sensory perception of bitter taste; G protein-coupled receptor signaling pathway; sensory perception of taste
Cellular component: membrane; plasma membrane
Genetic constraint (gnomAD): Loss-of-function variants: 0 observed, 0.0826 expected, observed/expected ratio (o/e) 0, 90% interval 0 to 1.89. That is too few expected variants to judge how well the gene tolerates losing a copy. Missense variants: 406 observed, 384.46 expected, observed/expected ratio (o/e) 1.06, 90% interval 0.97 to 1.15. Synonymous variants: 158 observed, 142.66 expected, observed/expected ratio (o/e) 1.11, 90% interval 0.97 to 1.26.
Homologues: Orthologues: chimpanzee TAS2R9 (98% identical), macaque TAS2R9 (91% identical), rabbit TAS2R9 (73% identical), pig TAS2R9 (70% identical). Paralogues in human: TAS2R7 (49% identical), TAS2R8 (46% identical), TAS2R10 (39% identical), TAS2R3 (38% identical), TAS2R31 (37% identical), TAS2R46 (37% identical), TAS2R13 (37% identical), TAS2R30 (36% identical), TAS2R19 (35% identical), TAS2R20 (35% identical), TAS2R43 (35% identical), TAS2R42 (34% identical), and 11 more.
Diseases named in the same sentence as TAS2R9 in open-access papers:
TAS2R9 is named in the same sentence as 6 diseases in open-access papers, as found by Europe PMC text mining. Sharing a sentence is not in itself a finding about the gene and the disease. The quoted sentences say what the papers report.
diabetes (1 paper, 2020). "This study also looked at the relationship between the TAS2R9 genotype and diabetes in 953 participants from the Amish Family Diabetes study." (PMID 32521750, 2020).
pancreatic cancer (1 paper, 2023). "Proof-of-concept drug delivery experiments demonstrate that TAS2R9-targeted liposomes bind with high specificity to TAS2R9 recombinant protein and exhibit stromal colocalization in a pancreatic cancer xenograft model." (PMID 36986488, 2023).
tumor (2 papers, 2021 to 2023). "Taken together, these results demonstrate that TAS2R9-targeted delivery of SB225002 to PDAC stroma results in enhanced inhibition of tumor growth compared to free drug and untargeted liposome delivery." (PMID 36986488, 2023). "The discovery of TAS2R9 as a CAF-selective marker whose targeting can improve the anti-tumor effects of liposomal delivery of a CXCR2 inhibitor opens the door for the modulation of CAF activity as a potent therapeutic strategy in PDAC." (PMID 36986488, 2023). "Here, we demonstrated that small molecule drugs encapsulated in TAS2R9-targeted nanoparticles enhanced the inhibition of tumor growth in a PDAC xenograft model." (PMID 36986488, 2023). "Overall, it remains to be elucidated what role TAS2R9 plays in tumor pathogenesis, whether that role may lead to new biological insight, and whether it could be targeted to improve patient outcomes." (PMID 36986488, 2023). "Compared to control liposomes that are found non-specifically throughout the tumor sections, the incorporation of TAS2R9-targeting peptides shifted the liposomal distribution, favoring PDAC stroma." (PMID 36986488, 2023). "Putative GPR15 co-expressed genes, such as TACR1, TAS2R9, SPDYE4, or GPR182, could be a more specific sign for tumor cells of adenocarcinoma or for healthy epithelial cells from which the tumor originates since all four genes were not expressed in GPR15+CD3+ lymphocytes." (PMID 34639163, 2021).
cancer (1 paper, 2023). A tumor composed of atypical neoplastic, often pleomorphic cells that invade other tissues. "Leveraging publicly available databases, we surveyed the status of TAS2R9 mutations and mRNA expression in human cancers." (PMID 36986488, 2023). "Beyond its role in the gustatory system, TAS2R9 expression also serves as an indicator of patient prognosis across multiple cancer types." (PMID 36986488, 2023). "Analysis of TAS2R9 gene expression revealed elevated mRNA expression in 7.33% (11/150) of curated PDAC patients from the TCGA pan-cancer atlas database." (PMID 36986488, 2023). "While mounting evidence points to a role of bitter taste receptors in cancer epithelial cells and in Tuft cells, this report, is to our knowledge, the first indication that TAS2R9 is expressed on CAFs." (PMID 36986488, 2023). "Analysis of 10,953 patient samples across 32 cancer types from the TCGA pan-cancer atlas database revealed that TAS2R9 was altered in 1.9% (211/10,953) of samples with a somatic mutation frequency of 0.5%." (PMID 36986488, 2023). "In particular, the revelation that TAS2R9 mRNA expression is of prognostic significance in several cancers suggests its role could be tissue-specific or context-dependent." (PMID 36986488, 2023). "Thus, an expanded analysis into how TAS2R9′s protein interaction network differs in tumors could help explain its role in tumorigenesis and the prognostic value of its mRNA expression across multiple cancer types." (PMID 36986488, 2023).
TAS2R9 also shares sentences with these, for which no sentence is quoted: acute myeloid leukaemia (1 paper); head and neck squamous cell carcinoma (1).